AQP4 (aquaporin 4)
Diseases named in the same sentence as AQP4 in open-access papers (continued):
Sharing a sentence is not in itself a finding about the gene and the disease.
Stroke (continued). "The expression of these channels are increased following stroke, and AQP4, EAAT 1/2, and CX43 have been reported to play important roles in the mediation of astrocyte end-feet swelling." (PMID 32415357, 2020). "Perturbation of AQP4 expression or disruption in the polarity of the AQP4 protein leads to glymphatic dysfunction, which have been shown in several neurological diseases including stroke, Alzheimer's disease and traumatic brain injury (TBI)." (PMID 32765412, 2020). "Since astrocyte function including expression of Aqp4 water channels is critically involved in edema formation following stroke, we further addressed the expression of Aqp4 in the time course of ischemia from 30 min to 4 h after ischemia induction." (PMID 30744693, 2019). "2-(nicotinamide)-1,3,4-thiadiazole (TGN-020) was shown to serve as a potent AQP4 inhibitor in an ischemic rodent stroke model." (PMID 30691235, 2019). "Post stroke levels of miR-130b are significantly reduced, and continue to decrease over 24-48 hours, allowing for increased translation of AQP4." (PMID 31011481, 2019). "The infarct volume, the reactive astrocytes and microglia, and the water regulatory protein aquaporin 4 (AQP4) were examined at 28 days after stroke." (PMID 31382635, 2019). "It has been shown that AQP4 gene knockout can alter the pathophysiological processes of neurological diseases, such as stroke and AD." (PMID 33817204, 2019). "In some conditions, such as hydrocephalus and stroke, the role of AQP4 has been studied for some time, while, in other diseases such as AD the role for AQP4 emerged only recently." (PMID 30691235, 2019). "Following MCAo in mice, AQP4 expression has been shown to be temporarily reduced or lost around 24 h post stroke during the reperfusion phase, and a partial recovery by 72 h post stroke." (PMID 30967147, 2019). "AQP4 deletion has been found to protect adult mice brain from edema in stroke models, which suggests that AQP4 is closely related to edema." (PMID 29540536, 2018). "Accumulating evidence has proven that AQP4 expression after cerebral ischemia is upregulated and that AQP4 knockdown reduces cytotoxic edema during stroke." (PMID 29057271, 2017). "This role of AQP4 in brain edema indicates that astrocytes are the major cell type involved in cytotoxic edema during pathological processes such as stroke." (PMID 29057271, 2017). "Our recent data indicate that Ex-4 treatment reduces stroke-induced frontal cortex edema, endoplasmic reticulum stress, apoptosis, and upregulation of aquaporin 4, glial fibrillary acid protein, and ICAM-1." (PMID 27296974, 2016). "AQP4 expression is both spatially and temporally regulated based on the type of stroke model, with AQP4 downregulation noted in cytotoxic edema, and an upregulation observed at the onset of vasogenic edema, potentially serving to accelerate water clearance." (PMID 27438832, 2016). "In an MCAO mouse model, T3 and T2 administered post-stroke mitigated edematous swelling via the downregulation of AQP4 expression." (PMID 27438832, 2016). "Following the occurrence of stroke, AQP4 expression presents two peaks despite the time variations among individual observations." (PMID 27242440, 2016). "Clinical utilization of AQP4 modulators is complicated by the bimodal role that AQP4 plays in stroke progression." (PMID 27438832, 2016). "On the one hand, reactive gliosis, indicated by increasing GFAP and AQP4 expression, is a sign of astrocyte swelling at the early stage of mild stroke and in the penumbra of severe stroke." (PMID 27242440, 2016). "These facts allow us to conclude that AQP4 expression and localization in stroke are correlated with the extent and stage of brain edema formation, which allows different groups of astrocytes to respond to ischemic insults differentially." (PMID 27242440, 2016). "This review briefly introduces the structure and function of AQP4 and focuses on the effects of AQP4 on stroke." (PMID 27529222, 2016).
Stroke (continued). "AQP4 knock-out mice were protected from the formation of cytotoxic edema in a stroke model, providing an explicit target for managing this condition." (PMID 26013827, 2015). "As is known that aquaporin-4 (AQ4) plays an important role in the formation of brain edema during stroke." (PMID 25914628, 2015). "These landmark experiments showed that spatiotemporal up-regulation of AQP4 is multi-factorial and dependent on differences between stroke model and type, species and age, and severity of the insult." (PMID 25904843, 2015). "In the rodent stroke model of transient occlusion of the middle cerebral artery, AQP4 immunoreactivity was rapidly reduced, primarily in regions with vascular damage." (PMID 26489685, 2015). "AQP4 has been shown to be important for brain edema formation following traumatic brain injury, stroke, and meningitis." (PMID 26013827, 2015). "In α-syntrophin-KO mice, deletion of AQP4 reduced hypo-osmolar edema following experimental stroke more than in wild-type mice." (PMID 25904843, 2015). "Subcellular localization and expression of Aqp4 was examined in rats subjected to experimental stroke." (PMID 26419740, 2015). "The identification of modulators and inhibitors of AQP4 offer new therapeutic avenues in the hope of reducing the extent of morbidity and mortality in stroke." (PMID 25904843, 2015). "Deletion of AQP4 has been shown to reduce the effects of cytotoxic edema and improve outcome after stroke." (PMID 24341850, 2014). "A significant decrease in AQP4-postive cells number was observed in the TT/Stroke group at 1 day and 2 days after ischemia when compared with the Stroke group (p<0.05)." (PMID 24416250, 2014). "A significant reduction in the expression of AQP4 was demonstrated in the TT/Stroke group when compared with stroke group at 1 hour, 2.5 hours, 7.5 hours,1 day and 2 days after ischemia (p<0.05)." (PMID 24416250, 2014). "TBI, stroke, and hypoxia alter the expressions and functions of AQP-4, HIF-1, and the MMP’s; these in turn affect edema formation, BBB disruption, and alterations in brain interstitial fluid circulations." (PMID 25251220, 2014). "Recently, AQP4-m1 mRNA and protein were found to increase quickly after stroke onset, while AQP4-m23 remained the same." (PMID 22778741, 2012). "Conversely, in a preconditioning stroke model, a higher induction of AQP4 was correlated with edema reduction." (PMID 22778741, 2012). "Osmotic gradients can also play an important role, and recently, high AQP4 expression was observed in hypersaline treatment after stroke correlating with decreased edema formation at 48 hours." (PMID 22778741, 2012). "Blocking AQP4 function, as seen in the studies of water intoxication and stroke, decreases the rate of edema formation and enhances survival." (PMID 21119879, 2010). "Two peaks of AQP4 expression were observed 1h and 48h post stroke, coinciding with the two peaks of hemispheric swelling." (PMID 21119881, 2010). "AQP4 knock-out mice display reduced cerebral edema in response to water intoxication and stroke and improved clinical indices of survival and neurological status." (PMID 21119881, 2010). "Data from immunostaining and protein quantification in human and animal tissues demonstrate up-regulation of AQP4 expression in primary brain tumours and stroke, and after traumatic brain injury." (PMID 21119879, 2010). "qPCR of RiboTag-IP’dmRNA from isolated microvessels after stroke revealed enrichment of astrocyte markers Aqp4 and Gfap, as well as depletion of vascular markers including Pecam1, Cldn5 (endothelial cells), Pdgfrb (pericytes), and Acta2 (vascular smooth muscle cells)." (PMID 39796165, 2025). "Indeed, one study noted that by 3–5 days post-stroke, AQP4-null mice actually showed more edema and worse lesion encapsulation than wild type, presumably due to impaired fluid clearance." (PMID 40943104, 2025).
Stroke (continued). "Future drugs might more selectively target the AQP4-calmodulin interaction or other anchors (e.g., the AQP4-α-syntrophin binding) to achieve a similar effect with fewer side effects in stroke patients." (PMID 40943104, 2025). "AQP4 expression is immediately and significantly increased in the lesion core, and then AQP4 expression in the lesion core was gradually decomposed within several hours after stroke, and only expressed in the peri-lesion." (PMID 40837880, 2025). "It is possible that re-localisation of AQP4 to astrocyte end feet may coincide with restoration of CSF tracer distribution to pre-stroke levels, but this is yet to be investigated." (PMID 40533800, 2025). "Additionally, acute AQP4 inhibition with TGN-020 reduces early-phase cerebral edema and promotes post-stroke recovery by attenuating peri-infarct astrocyte proliferation and AQP4 depolarization." (PMID 40144621, 2025). "The role of AQP4 water channels in stroke recovery is controversial." (PMID 38822994, 2025). "AQP4 redistribution also occurs in early stroke; AQP4 depolarizes (spreads) across astrocyte processes, while, later, it may repolarize at the endfeet to enhance fluid clearance." (PMID 40943104, 2025). "In any case, such findings hint that measuring AQP4 or related extracellular vesicles in blood might help prognosticate edema development or recovery potential in stroke patients." (PMID 40943104, 2025). "Tackling the challenge of AQP4 in stroke will require embracing its dual nature." (PMID 40943104, 2025). "Research indicates that AQP4 levels in the blood may peak within 24 to 48 h following a stroke, coinciding with the progression of BBB disruption and astrocyte damage." (PMID 40142325, 2025). "The altered localisation of AQP4 after stroke could explain some of the reduction in CSF tracer distribution." (PMID 40533800, 2025). "For example, a soluble small-molecule AQP4 inhibitor could be administered in the hyperacute phase of stroke (first few hours) to delay astrocytic swelling, then washed out or counteracted by a second agent that promotes AQP4 activity in the subacute phase." (PMID 40943104, 2025). "One interpretation is that higher detectable AQP4 in blood reflects greater astrocytic membrane shedding from an initially robust edema response that subsequently allows fluid clearance, essentially a marker that AQP4 has been activated and possibly aided in post-stroke fluid redistribution." (PMID 40943104, 2025). "A pilot study of AIS patients treated with intravenous thrombolysis (t-PA) revealed that baseline serum AQP4 levels were inversely correlated with infarct size and neurological severity at admission, as measured by the National Institutes of Health Stroke Scale (NIHSS)." (PMID 40564125, 2025). "Gene therapy is likely too slow for stroke, but nano-delivery systems might one day deliver short-acting AQP4 blockers to penumbral tissue." (PMID 40943104, 2025). "AQP4 expression and function in the brain are tightly controlled at multiple levels beyond transcription, and these regulatory mechanisms become especially relevant during stroke and hypoxic injury." (PMID 40943104, 2025). "In addition, Mestre and colleagues connected the enhanced fluid influx post-stroke, during SD, respectively, with a disruption of the physiological functions of AQP4 after stroke." (PMID 38822994, 2025). "Another opportunity is leveraging the body’s own sleep and glymphatic mechanisms; induced sleep or slow-wave oscillations post-stroke could enhance glymphatic clearance (which is AQP4-dependent) and, thus, vasogenic edema resolution." (PMID 40943104, 2025). "On the other hand, an AQP4 activator given in late stroke could aid fluid removal but would be harmful if given during the initial ischemic swelling." (PMID 40943104, 2025). "Recent work suggests that serum AQP4 levels could serve as a biomarker of stroke severity and recovery." (PMID 40943104, 2025).
Stroke (continued). "This suggests that differences in AQP4 expression or function (determined by genotype) might alter how individuals’ brains handle edema after stroke." (PMID 40943104, 2025). "Moreover, the same calmodulin inhibitor decreases the expression of AQP4 proteins and reduces oedema, while increasing glycogen metabolism in the early acute phase in a post-stroke mouse model." (PMID 38472255, 2024). "Additionally, it has a protective role on stroke outcomes, as previously suggested by various preclinical studies investigating its impact on the ischemic brain using AQP4 knockout mice." (PMID 39596535, 2024). "Our findings underscore AQP4's pivotal role in modulating post‐stroke neuroinflammation." (PMID 39444081, 2024). "The AQP-4 is important in both the development and recovery from stroke and cerebral edema." (PMID 39201439, 2024). "Connexin 43 (CX43), aquaporin 4 (AQP4), and apolipoprotein E (APOE) are generally considered to be astrocyte-derived proteins and are closely associated with pathogenesis of ischemia or stroke." (PMID 39766455, 2024). "If AQP4 exacerbates ischemic injury through its involvement in neuroinflammation, modulating its activity or expression could ameliorate outcomes post‐stroke." (PMID 39444081, 2024). "The aquaporin‐4 (AQP4) water channel is abundantly expressed in the glial cells of the central nervous system and facilitates brain swelling following diverse insults, such as traumatic injury or stroke." (PMID 38102893, 2024). "By blocking AQP4, thyroid hormone therapy also lowered CE and may be neuroprotective for stroke patients." (PMID 38808718, 2024). "Following a stroke, the expression of AQP4 was significantly increased between 6 and 48 h, which may aggravate the development of cytotoxic oedema." (PMID 37702572, 2024). "RAs showed intense AQP4 expression 72 h post-stroke, indicating the initiation of astrogliosis." (PMID 39596535, 2024). "We investigated AQP4's role in astrocytes during post‐stroke inflammation." (PMID 39444081, 2024). "Indeed, preconditioned extracellular vesicles derived from hypoxic microglia alleviate post-stroke AQP4 depolarization, restore disrupted cerebrospinal fluid flow, and reduce astrogliosis and neuroinflammation." (PMID 39484304, 2024). "AQP‐4 channels are upregulated after stroke and may contribute to increased cerebral edema post‐stroke." (PMID 38041607, 2024). "Previous work showed that mCRP was deposited in the cortical microvessels of individuals who died from either stroke or AD, and this was concomitant with expression of inflammatory markers, such as CD68 and interleukin-1 beta (IL-1β), and also aquaporin 4, associated with lymphatic Aβ clearance." (PMID 38899254, 2024). "Some studies on strokes showed that the acute inhibition of AQP4 promoted neurological recovery by diminishing brain edema at the early stage and attenuating peri-infarct astrogliosis and AQP4 depolarization at the subacute stage." (PMID 39484304, 2024). "On the other hand, deletion of AQP4 can obviously prevent the cytotoxic edema after stroke." (PMID 37238624, 2023). "Impaired polarization (“depolarization”) of AQP4 may therefore present a novel target for stroke treatment." (PMID 37554272, 2023). "In fact, reallocation of AQP4 away from the perivascular endfeet has also been observed in post-stroke dementia, suggesting that it may be a common mechanism underlying different forms of cognitive dysfunction." (PMID 36859364, 2023). "It is concluded that mislocalization of AQP4 from perivascular end-feet to the cell body in reactive astrocytes is associated with the reduction of efficacy of the glymphatic system and the onset of pathological cerebral findings following AD, TBI, and stroke." (PMID 37048052, 2023). "Also, AQP4 expression in astrocytes has important implications in neuroinflammation secondary to ischemia, and AQP4 knockout mice exhibit exaggerated post-stroke microglial reactivity." (PMID 37483351, 2023).
Stroke (continued). "Some studies have shown that AQP4 knockout leads to less swelling of the brain after a stroke." (PMID 37767530, 2023). "Further studies applied a stroke model, where some mice also received an intracisternal tracer infusion of rhodamine B. As such, these in vivo studies involved the analysis of AQP4 polarization, CSF flow, astrogliosis, and neuroinflammation as well as ischemia-induced brain injury." (PMID 37554272, 2023). "Likewise, preconditioned EVs diminish periinfarct AQP4 depolarization, impaired CSF flow, astrogliosis, and inflammation in the stroke mouse model." (PMID 37554272, 2023). "Whether or not different EV concentrations and dosages may differentially affect post-stroke AQP4 polarization, astrogliosis and neuroinflammation under such conditions has to be addressed in future studies." (PMID 37554272, 2023). "On the flip side, AQP4 knockout mice exhibit exaggerated post-stroke microglial reactivity, and this may explain the heightened microglial reactivity we see in COVID-19 ION." (PMID 37483351, 2023). "Recent studies have shown that the glial water channel (aquaporin-4) and the glymphatic system could be involved in the pathophysiology of neurological disorders, including stroke, and implementing their therapeutic potential of stroke." (PMID 35203945, 2022). "In addition, WB and RT-PCR assay indicate that the level of AQP-4 in the ischemic brain is decreased in the ABCA1−B/−B-T2DM stroke mice (p < 0.05, n = 6/group)." (PMID 35572941, 2022). "Finally, the sixth group comprised one study dealing with the prognostic value of AQP-4 in the functional recovery of stroke patients." (PMID 36278689, 2022). "Furthermore, mislocalization and altered expression of AQP4 is a common denominator in a variety of neurological conditions, ranging from stroke to mesial temporal lobe epilepsy and Alzheimer’s disease." (PMID 35518645, 2022). "Regardless, the traditional or newly-found mechanism of edema both suggest that acute inhibition of AQP4 could reduce post-stroke edema at the early stage." (PMID 35592320, 2022). "These factors include knockout of AQP4, sleep, anaesthesia incorporating the α2 adrenoceptor agonists xylazine or medetomidine, age, posture, small vessel disease, idiopathic normal pressure hydrocephalus (iNPH), stroke, and hypercapnia (see Sect." (PMID 35115036, 2022). "Studies of mice that suffer a loss of perivascular AQP4 following genetic deletion of α-syntrophin have shown that this pool of AQP4 is involved in a number of critical functions including potassium homeostasis and edema formation following stroke, or hyponatremia." (PMID 35518645, 2022). "A study has shown that thyroid hormone therapy can weaken brain edema by inhibiting AQP4 and may have neuroprotective effects on post-stroke patients." (PMID 36061592, 2022). "Besides, insulin-like growth factor 1 (IGF1) and aquaporin-4 (AQP4) decreased, while matrix metalloproteinase-9 (MMP9) heightened after stroke in brain ABCA1 deficiency mice." (PMID 35935038, 2022). "Here, via the blockage of Na(+)-K(+)-2Cl(-) co-transport and AQP4 inhibition, a decrease in cerebral edema in post-stroke rodents was demonstrated, suggesting another potential pharmacological approach to conditions whereby fluid imbalances or edematous changes manifest." (PMID 36498538, 2022). "If irreversible neural damage after stroke can be reduced by regulating AQP4, the protection of cognitive function may be achieved to some extent." (PMID 35111362, 2022). "Notably, the decreased polarity of AQP4 expression is concomitant with a significant suppression of glymphatic function after stroke." (PMID 36582539, 2022). "Furthermore, in this same study, AQP4 was found to be an independent predictor of good neurological outcome in stroke patients, which is in agreement with our results." (PMID 33801197, 2021). "The results showed that the expression of AQP4 was increased in stroke mice compared to sham mice." (PMID 35095486, 2021).